FOXM1 (forkhead box M1)
Diseases named in the same sentence as FOXM1 in open-access papers (continued):
Sharing a sentence is not in itself a finding about the gene and the disease.
cancer (continued). "Efficient reduction of PD‐L1 expression could be achieved by inhibiting FOXM1 protein via siRNA‐mediated knockdown or TST treatment under conditions that mimic malignant tumors." (PMID 35975458, 2022). "It is hypothesised that upregulation of GDF-15 combined with decreased expression of FOXM1 act together to form a CBD-dependent antiproliferative pathway across numerous cancer types." (PMID 35954477, 2022). "And this result suggests the possibility that DFS may also have a therapeutic effect on GBM, considering the mechanism that DFS exerts anti-cancer effects by acting on FOXM1." (PMID 35978012, 2022). "Additionally, we verified that FOXM1-PROTAC had the same inhibitory effect on different cancer cell lines." (PMID 36171633, 2022). "FOXM1 regulatory network is a major predictor of adverse outcomes in various human cancers." (PMID 35680842, 2022). "In addition, as previously introduced, the FOXM1-positive index is an oncogene for cancer development and a marker for cell proliferation, and the Caspase-3 is a marker for cell apoptosis." (PMID 35978634, 2022). "However, the amount of HMGA1 protein in cancer tissue correlated with the amount of FOXM1 and G6PD, with which HMGA1 forms a common pathway for transcriptional regulation and which were similarly associated with TNM stage and overall survival." (PMID 35948739, 2022). "However, while PD-L1 regulation has been extensively studied in cancer cells, the specific link between PD-L1 and FOXM1 has received less attention." (PMID 36171633, 2022). "In addition, expression levels of several well-characterized cancer stemness regulators, such as FOXM1 and EZH2, also showed a strong correlation with mRNAsi among the HCC patients of the TCGA-LIHC cohort." (PMID 35158838, 2022). "However, the amount of HMGA1 protein in cancer tissue was correlated with the amount of FOXM1 and G6PD." (PMID 35805937, 2022). "FOXM1 plays a key role in proliferation and cell cycle progression through transcriptional activation of a G2/M-specific gene network, and increased FOXM1 gene expression and its transcriptional signature have been detected in many cancer types." (PMID 35481418, 2022). "Interestingly, according to recent evidence, proteasome inhibitors abrogate FOXM1 function in cancer." (PMID 35955438, 2022). "In this study, we focus on FOXM1 because it is involved in cancer stemness and metastasis." (PMID 36591565, 2022). "Numerous evidences indicate that FOXM1 expression is increased in a variety of human cancers." (PMID 35039475, 2022). "MELK has been shown to activate mitotic regulatory genes by activating FOXM1 in other cancers." (PMID 36151566, 2022). "Lamin-A, C profiles appear strikingly similar to those for the mechanosensitive factors Vinculin, Yap1, and Piezo1, whereas datasets for lamin-B1 align with and predict regulation by the cell cycle transcription factor, FOXM1, and further predict poor survival across multiple cancers." (PMID 35719698, 2022). "A combination of HELLS and FOXM1 may serve as a biomarker for early cancer detection, malignant transformation, and progression in HNSC and OSCC." (PMID 35774795, 2022). "Higher m6A modification was found on FOXM1 mRNA in cisplatin resistant cancer cells." (PMID 36291811, 2022). "The overexpression of FOXM1 is observed in various cancers, including CRC." (PMID 35346234, 2022). "As a member of the forkhead superfamily, FOXM1 regulates the tumorigenesis of various cancer types." (PMID 36291811, 2022). "Targeting the FOXM1 pathway is an intriguing strategy for combating cancer." (PMID 36357378, 2022). "Nevertheless, there is little research on FOXM1 in pan-cancer." (PMID 36435510, 2022). "In conclusion, this study indicated that FOXM1 could serve as a prognostic biomarker for most types of cancers and played a crucial role in the tumor immune microenvironment." (PMID 36435510, 2022).
cancer (continued). "Increased E2F1 and FOXM1 in cancers with high levels of TRPM2 may contribute to transcriptionally increased expression of α1, β1 and β5 integrins, and greater migration and invasion." (PMID 36446940, 2022). "Additionally, the Forkhead box (FOX) family of transcription factors (FOXF1, FOXS1, FOXM1, FOXK1, FOXP4, and FOXC1) play a role in cell differentiation and proliferation and are implicated in cancer and drug resistance." (PMID 35854219, 2022). "Importantly, our data further demonstrated that PDK1 expression was critical for FOXM1‐mediated cancer growth in vitro and in vivo." (PMID 35656815, 2022). "The inhibition of FOXM1 can terminate the proliferation of cancer cells." (PMID 35593206, 2022). "Multiple microenvironmental factors are critical for promoting cancer progression; therefore, we investigated whether these factors affect FOXM1 expression status in NPC cells." (PMID 35656815, 2022). "Studies have shown that FOXM1 strongly enhances cancer cellβ-catenin nuclear translocation." (PMID 36530974, 2022). "In cancer cells, FOXM1apt mainly binds to FOXM1 and inhibits FOXM1’s transcriptional activities." (PMID 36091772, 2022). "FOXM1 has proven to be an effective prognostic biomarker for most cancers." (PMID 36435510, 2022). "FoxM1 is an extensively studied member of the Forkhead Box family and is considered a pharmaceutical target for treating many malignant tumors since the discovery of a linkage between the activation of FoxM1 and oncogenes, such as members of the Ras-MAPK and sonic hedgehog pathways." (PMID 35884976, 2022). "Therefore, the expression of FOXM1 has become the focus of cancer testing and preventive drug development." (PMID 36613925, 2022). "Past works have indicated the tumor-promoting role of FOXM1 in several cancers." (PMID 35799265, 2022). "BUB1B is positively correlated with FOXM1 in all the cancer types from TCGA." (PMID 35847923, 2022). "FOXM1 is a critical driver of proliferation and it is overexpressed in a broad range of cancers." (PMID 35743036, 2022). "Additionally, FoxM1 primarily participates in tumorigenesis through transcriptional regulation of target genes involved in cancer initiation, progression, metastasis, invasion and drug resistance." (PMID 35884976, 2022). "As previously reported, FOXM1 expression was essential for cancer progression." (PMID 35628623, 2022). "FOXM1 is expressed in many cancers and has been demonstrated to be directly regulated by the canonical Wnt/β-catenin signaling pathway, contributing to the development of the cancer phenotype, including proliferation, decreased apoptosis, metastasis, and drug resistance." (PMID 35053606, 2022). "FOXM1 is a transcriptional factor that plays a pivotal role in cancer development." (PMID 35313071, 2022). "The nuclear translocation of FOXM1 has been highlighted as a prominent feature of many cancers." (PMID 35975458, 2022). "Inhibition of FOXM1 transcription factor function is a potential strategy in cancer treatment." (PMID 35680842, 2022). "Forkhead box M1 (FOXM1) is an important transcription factor that is overexpressed in many cancers." (PMID 36591565, 2022). "This novel peptide based FOXM1-PROTAC showed two main advantages: on the one hand, the antagonistic peptide FIP-1 not only can bind with FOXM1 and recruit E3 ubiquitin to degrade FOXM1 through pomalidomide, but also can inhibit the effects of FOXM1 in cancer progression." (PMID 36171633, 2022). "In human cancer cells, FOXM1 binds to the promoters of SKP2 and CKS1 and activates them." (PMID 34680943, 2021). "FOXM1 is therefore a potential therapeutic target in cancer therapy potentialy inhibited by PL." (PMID 33953844, 2021). "Overall, the DNA loops from the reconstructed genome structure contained bioprocesses involved in transcription, such as the pre-transcriptional initiation complex and RNA polymerase II initiation complex, and transcription factors involved in cancer, such as Foxm1 and CREB3." (PMID 34828279, 2021).
cancer (continued). "FOXM1 is a FOX transcription factor that regulates multiple processes in cancer." (PMID 34768915, 2021). "Whether specific transcription factors symmetrically or asymmetrically regulate F/R-BDP activity is a key question as the FOXM1/RHNO1 expression ratio increased in cancer vs. normal." (PMID 33890574, 2021). "However, it seems challengeable to explain the importance of FOXM1 in cancer by only describing the ability of FOXM1 (FOXM1B/C) to regulate the transcription of over 200 target genes that are primarily involved in cell proliferation." (PMID 33314660, 2021). "Thus, FOXM1 inhibition by STL can sensitize cancer cells to treatments based on both direct and indirect DNA damage induction." (PMID 34262016, 2021). "Additionally, the authors showed that FOXM1 expression correlates with RS biomarkers in The Cancer Protein Atlas data from several cancer types, including HGSC." (PMID 33890574, 2021). "FOXM1 is a transcriptional master regulator of several hallmarks of cancer." (PMID 34205406, 2021). "To determine whether copy number status associates not only with FOXM1 but also RHNO1 expression in HGSC, we analyzed TCGA and Cancer Cell Line Encyclopedia (CCLE) data." (PMID 33890574, 2021). "Measuring phospho-FOXM1 may provide more insight into FOXM1 activation status in cancer and should be emphasized in future investigations." (PMID 34205406, 2021). "People were interested in the therapeutic target of FoxM1 in cancer." (PMID 35173608, 2021). "UA may mediate the enhancement of PTX induced inhibition of cancer cell growth through indirect mechanisms through inactivation of Akt/FOXM1 signaling pathway." (PMID 34768915, 2021). "Recently, researchers found that the expression of FOXM1 was positive correlated with FOXP3 (the specific molecular marker of Tregs) and FOXM1 may induce immune suppression via recruiting FOXP3 positive Tregs in cancer therapy." (PMID 33892811, 2021). "Forkhead box protein M1 (FOXM1) is a crucial regulator of cancer development and chemoresistance." (PMID 34381718, 2021). "Forkhead box M1 is a key transcription factor that plays an important role in the development of embryos, the homeostasis of mature tissues, and the occurrence and progression of malignant tumors." (PMID 34621746, 2021). "It is also known that miR-143 could interact with multiple circRNAs, such as circ-FOXM1 and circFOXO3, to participate in cancer biology." (PMID 34749774, 2021). "Therefore, uncovering the regulatory mechanisms of FOXM1 will provide new insights into the pathogenesis of PC as well as new therapeutic strategies against this deadly cancer." (PMID 34584067, 2021). "Given its explicit oncogenic nature, FOXM1 has emerged as a promising target for cancer treatment." (PMID 33937262, 2021). "A seminal early study showed that FOXM1 and several of its transcriptional targets, such as AURKB and CCNB1, rank in the top 70 genes for which overexpression is associated with chromosomal instability (CIN) in pan-cancer (named the CIN70 signature)." (PMID 34205406, 2021). "FOXM1 is a transcription factor that regulates the expression of cell cycle genes essential for DNA replication and mitosis and plays a role in the control of cancer cell proliferation." (PMID 33952272, 2021). "Accordingly, the powerful ability of FoxM1 inhibition in resistant cancer cells to induce apoptosis in response to Artemisinin therapy points towards its encouraging therapeutic potential during cancer progression." (PMID 34900697, 2021). "FOXM1 is known as a master regulator of proliferation, metastasis, and cell cycle in cancer cells." (PMID 34335925, 2021). "Accordingly, there is high interest in FOXM1 as a cancer therapeutic target." (PMID 33890574, 2021). "In most human cancers, FOXM1 is overexpressed, an indicator of poor prognosis for cancer patients." (PMID 33818655, 2021).
cancer (continued). "Herein, our findings have provided a new insight into the PKM2‐induced tumor glycolysis and angiogenesis that was potentiated by multiple protein–protein interactions mediated by FOXM1D, and suggest that FOXM1 may be a promising target for cancer therapeutics." (PMID 33314660, 2021). "Knockdown of FOXM1 increases sensitivity to radiation therapy in quiescent and cancer stem cells." (PMID 33867999, 2021). "Moreover, a recently developed FOXM1 inhibitor reduces β-catenin abundance and activity in different cancer cell lines, and attenuates tumor growth in mouse xenograft models." (PMID 34298659, 2021). "Besides, in different types of tumors, another transcriptional target of STAT3 has emerged for its importance in conferring radioresistance to the cancer cells: Forkhead box protein M1 (FOXM1)." (PMID 34141616, 2021). "These mitochondrial genes included MT-CO1, MT-CO2, MT-CO3, MT-ATP6 and 8, and MT-ND2,3,4,5, and 6 (left), which are critical for energy production and cancer cell survival and likely important for thwarting of therapy effectiveness observed in these FOXM1 inhibitor-resistant cells." (PMID 34944900, 2021). "Increased FOXM1 expression in cancer promotes cell cycle progression and cell proliferation." (PMID 34205406, 2021). "We postulate that cancer cells have a selective advantage for FOXM1 and RHNO1 co-expression since FOXM1 drives RS and downstream oncogenic phenotypes such as genomic instability, while RHNO1 helps mitigate FOXM1-induced RS to a level more favorable to cancer cell survival." (PMID 34205406, 2021). "Overexpression of FOXM1 has been frequently reported in various types of cancers, including GC." (PMID 33407516, 2021). "Namely, FOXM1 promotes epithelial-mesenchymal transition and metastasis formation for breast and various other cancers, RRM2 contributes to poor survival and tamoxifen resistance development, while expression levels of CDK1, PLK1 and RACGAP1 were shown to be prognostic markers." (PMID 33852600, 2021). "In cancer glioma cells, downregulation of FOXM1 by siRNA reduces SIRT1 expression." (PMID 34680943, 2021). "FOXM1 is also able to change the cancer epigenome in breast cancer." (PMID 33572108, 2021). "FOXM1 play roles in cancer related processes, such as invasion and metastasis, but this might be linked with invasion and metastasis of pituitary prolactinoma." (PMID 33709028, 2021). "Moreover, FOXM1 is a known downstream factor of the Akt signaling cascade and plays an important role in cancer cell growth and metastasis." (PMID 34073071, 2021). "Thiazole antibiotics that specifically target FOXM1 inhibited cancer growth, inducing apoptosis." (PMID 33804240, 2021). "In the majority of cancers, overexpression of FOXM1 induces the progression of the disease." (PMID 33829064, 2021). "First, comprehensive understanding of FOXM1 regulation will provide merit for cancer therapy." (PMID 33668819, 2021). "In addition, we also demonstrated that FDI-6 specifically targeted cancer cells with a high FOXM1 expression, which can be very important for cancer treatment." (PMID 34206484, 2021). "In addition, 9 of the 18 GII-specific core regulators were annotated to cell cycle pathway, such as MYBL2, FOXM1, previously known to be related to cancer abnormal cell cycle." (PMID 34001209, 2021). "Transgenic mouse models have also been utilized to define the functions of FOXM1 in cancer." (PMID 34205406, 2021). "FOXM1 is a key transcription factor regulating cancer cell growth and metastasis." (PMID 34768915, 2021). "More surprisingly, FOXM1 plays a vital role in many other cancers." (PMID 33912448, 2021). "Nevertheless, little is known whether FOXM1 transcriptionally activates the expression of miRNAs in cancer." (PMID 33867818, 2021). "This led us to hypothesize that FoxM1 may regulate STMN1 at the transcriptional level in cancer cells." (PMID 33526768, 2021).
cancer (continued). "Numerous studies had proven that FOXM1 promoted the progression of various cancer types." (PMID 34966670, 2021). "FOXM1 depletion has been reported to inhibit cancer cell growth and trigger apoptosis." (PMID 34206484, 2021). "Upregulation and activation of FOXM1 in cancer can contribute to numerous phenotypes, including cell proliferation, cancer stemness, genomic instability, drug resistance, protection from oxidative stress, altered metabolism, invasion, metastasis, angiogenesis, and inflammation." (PMID 34205406, 2021). "Therefore, the FOXO3a-FOXM1 axis is actually a crucial therapeutic target for the treatment of cancer, particularly for overcoming drug resistance." (PMID 33466512, 2021). "FOXM1 is overexpressed in various cancer types and positively correlates with poor prognosis." (PMID 34768915, 2021). "FOXM1 is also associated with the upregulation of inhibitor of apoptosis (IAP) genes, including survivin (BIRC5) and X chromosome-linked IAP (XIAP) in several cancers." (PMID 34205406, 2021). "AT1R probably took part in the CAV1 and FOXM1 signaling pathway in those cancer cells." (PMID 33673178, 2021). "Loss of the ATM-ATR signatures also suggest that AML cells with inhibited FOXM1/AKT activity may display higher sensitivity to anti-cancer therapy." (PMID 34381718, 2021). "FOXM1 is critical to the EMT/mesenchymal-epithelial transition (MET) process in carcinomas, but its role in UM remains unknown." (PMID 33428593, 2021). "FOXM1 promoted cell viability and reduced FOXM1 could rescue circular influence of circular PVT1-caused carcinoma induction." (PMID 33391456, 2021). "Novel strategies to target FOXM1 dependent cancers could include combinatorial therapies with inclusion of chemosensitizers." (PMID 33680951, 2020). "Overexpression of FoxM1 accelerates cellular proliferation and cancer progression." (PMID 32429421, 2020). "FOXM1, a known transcription factor, promotes cell proliferation in a variety of cancer cells." (PMID 32066721, 2020). "FOXM1 is an oncogenic transcription factor that is upregulated in a wide range of cancers." (PMID 32466459, 2020). "To further investigate whether any particular cancer-specific enhancers were linked to patient outcome, we performed survival analyses using cancer-specific enhancer probes linked to CENPA, FOXM1, or MYBL2." (PMID 32925947, 2020). "In this study, we hypothesized that RAME could exert anti-cancer effects since it downregulated the expression of FOXM1 target genes, according to our RNA sequencing data." (PMID 33053721, 2020). "The miRNA which target and regulate FOXM1 expression has widely been altered in various cancers." (PMID 33680951, 2020). "Moreover, inhibition of FOXM1 in cancer cells, such as those of breast, gastric, gallbladder and liver cancer, leads to cellular senescence." (PMID 32372224, 2020). "In addition to being a boon for the normal functioning of a cell, FOXM1 turns out to be a bane by manifesting in several disease scenarios including cancer." (PMID 33680951, 2020). "So it would be speculated that the deregulation on these molecules in cancer may affect the expression of FOXM1 transcription factor." (PMID 33680951, 2020). "It was reported that cisplatin-resistant cancer cell lines showed elevated FOXM1 levels." (PMID 33053721, 2020). "Therefore, FOXM1 is a promising therapeutic target for inducing anti-cancer effects in various cancer cells." (PMID 33053721, 2020). "This review mainly addresses the mechanisms by which FOXM1 is deregulated in cancer." (PMID 33680951, 2020). "FOXM1 is a known transcription factor which promotes cell proliferation in cancer cells." (PMID 32066721, 2020). "As most cancer cells exhibit uncontrolled cell cycles, the inhibition of FOXM1 could be an attractive strategy for the development of anticancer drugs." (PMID 32858881, 2020). "Accordingly, we further investigated whether the expression level of FOXM1 could be a prognostic marker for various types of cancers." (PMID 32858881, 2020).